NOX1 (NADPH oxidase 1)
Diseases named in the same sentence as NOX1 in open-access papers (continued):
Sharing a sentence is not in itself a finding about the gene and the disease.
Hypertension (continued). "Therefore, suggesting a positive correlation between PDI and Nox1 expression during the development of hypertension in MRA." (PMID 25870854, 2015). "Taken together, the increase in Nox1 and Nox4 and the reduction of eNOS expression in 12 week old arteries from SHR could be associated with the maintenance of hypertension." (PMID 25870854, 2015). "Overproduction of O·−2 from NOX1 and NOX 2 can cause renin release, smooth muscle cell proliferation, and decreased NO·, all of which lead to endothelial dysfunction and increased sympathetic tone that in turn cause hypertension." (PMID 25505418, 2014). "In a hypertension animal model, angiotensin II increased TIMP-1 mRNA level in both Nox1 deficient mice and wild type mice but increased TIMP-1 mRNA protein levels much more tremendously in Nox1 deficient mice than wild type mice." (PMID 24669283, 2014). "Nox1 is expressed in colon epithelium and smooth muscle and genetic deletion of Nox1 has no overt baseline phenotype but results in altered disease susceptibility including some forms of hypertension, vascular remodeling and atherosclerosis." (PMID 24992705, 2014). "Indeed, basal blood pressure, angiotensin-induced hypertension, and endothelium-dependent relaxation in spontaneously hypertensive rats depends—to some degree—on NOX1." (PMID 22648375, 2012). "The Nox family consists of seven distinct isoforms: Nox1 through Nox5, as well as Duox1 and Duox2, each playing a unique role in regulating ROS production and contributing to various physiological and pathological processes, including hypertension and vascular dysfunction." (PMID 39974735, 2025). "Indeed, endothelial cell Nox1 is required for hypertension in response to AngII, while NOX2 overexpression in endothelial cells further promotes blood pressure elevation in response to AngII and stimulates macrophage recruitment and the initiation of atherosclerotic plaque formation in ApoE−/− mice." (PMID 36139898, 2022). "In contrast to our initial hypothesis, inhibition with pharmacological inhibitors of Nox1/4 hasten these features of accelerated vascular ageing, while inhibition of Nox1 exerts only minor effects on perivascular inflammation or development of spontaneous hypertension in rats." (PMID 33131726, 2020). "Therefore, inhibiting ROS production by targeting Nox4 and Nox1 might provide better antioxidant therapies to prevent the transition from hypertension to chronic heart failure." (PMID 32831633, 2020). "Therefore, Nox1-derived ROS could contribute to increased wall thickness in hypertension development." (PMID 25870854, 2015). "Therefore, PDI could be a novel regulator of Nox1 signaling in resistance arteries contributing to oxidative stress and vascular dysfunction in hypertension." (PMID 25870854, 2015). "AngII-induced hypertension was significantly induced in NOX1−/− and PLC-β3∆SMC mice, whereas LCCA ligation-induced neointima formation was significantly suppressed in NOX1−/− and PLC-β3∆SMC mice." (PMID 38945956, 2024). "NOX1 and NOX2 promote vascular inflammation and remodeling, exacerbating conditions such as hypertension and atherosclerosis." (PMID 39456418, 2024). "Animal experiments have confirmed that NOX1 and NOX2 are involved in vascular growth and remodeling and play important roles in vascular diseases such as hypertension and atherosclerosis." (PMID 36860953, 2023). "The NOX1 and NOX2 oxidases are the primary sources producing ROS in the artery wall in hypertension and contribute to oxidative stress and vascular inflammation that trigger arterial remodeling." (PMID 36925635, 2023). "As cells of the immune system are activated in hypertension, they produce cytokines which act on the adjacent tissue to promote the synthesis of ROS derived from NADPH oxidase (NOX1 and NOX2)." (PMID 36310604, 2022).
Hypertension (continued). "In some disease conditions, including hypertension, activation of NADPH oxidase, especially NOX1 and NOX2 isoforms, promotes the synthesis of ROS, which causes the oxidation of BH4 to BH2, resulting in eNOS uncoupling." (PMID 36310604, 2022). "NOX1 is a significant source of ROS in cardiovascular diseases, including ANG II-dependent hypertension." (PMID 35204118, 2022). "Both O2•− and H2O2 are increased in vascular cells in experimental models of hypertension including SHR/SHRSP rats, DOCA rats, angiotensin II-induced mice, and transgenic mice overexpressing smooth muscle cell-specific NOX1." (PMID 36552639, 2022). "Subsequently, we used pharmacological inhibitors of Nox1 (ML171) and Nox1/Nox4 (GKT137831; 60 mg/kg), to modulate NADPH oxidase activity at the early stage of spontaneous hypertension and investigated their effects on perivascular inflammation and fibrosis." (PMID 33131726, 2020). "NOX1 and NOX2, together with their subunits, p47phox and p22phox, seem to be involved in the pathophysiology of hypertension." (PMID 30326648, 2018). "Several cardiac NAD(P)H oxidase comprising NOX1, NOX2, and NOX4, appears to be required for the oxidative mechanisms involved in the development of left ventricular hypertrophy in hypertension." (PMID 29156835, 2017). "Recent study suggests the role of certain dominant NOX family such as NOX1, NOX2, and NOX4 in contributing ROS-induced hypertensive LVH." (PMID 29156835, 2017). "In the vasculature, neither Nox1 nor Nox4 gene expression was affected by either hypertension or diabetes." (PMID 37253814, 2023). "In contrast, several in vivo reports pointed out that knocking down of NOX1 did not affect the blood pressure and the development of hypertension." (PMID 37134122, 2023). "Moving to Nox inhibition, the dual Nox1/4 inhibitor setanaxib (GKT137831) has been investigated in the experimental setting of doxorubicin-, angiotensin II-, and hypertension-induced cardiac remodeling, displaying cardioprotective effects based on antioxidant and antifibrotic action." (PMID 36295098, 2022). "Conversely, endothelial NOX1, NOX2, and NOX5 contribute to impaired vascular function, endothelial nitric oxide synthase (eNOS) uncoupling, and adverse vascular remodeling and hypertension." (PMID 36139898, 2022). "A direct causal role for Noxs in the development of hypertension has been demonstrated in mice lacking Nox1, Nox2, Nox4, or p47phox where Ang II-induced endothelial dysfunction and hypertension are blunted." (PMID 30334629, 2019). "Mechanical stretch upregulated Nox1 and Nox4 expressions but not Nox2, indicating the important role of Nox1 and Nox4 in mechanical stretch/hypertension-induced vascular remodeling." (PMID 26557089, 2015). "It has been reported that Nox1 overexpression in SMCs augments Ang II-induced hypertension and smooth muscle hypertrophy; moreover, the deletion of Nox1 alleviates elevated blood pressure and maintains endothelium-dependent vascular relaxation in Ang II-infused mice." (PMID 39721498, 2025). "Treatment with inhibitors targeting Nox1, Nox2, and Nox4 (such as apocynin, diphenyl iodide, gp91ds-tat, and GKT137831) in a mouse model of hypertension significantly improved vascular function, normalized blood pressure, and attenuated hypertension-induced cardiac remodeling (Schröder, 2014)." (PMID 39974735, 2025). "Contrary to the majority of evidence supporting the importance of NOX1 and NOX2 in short-term Ang II-induced hypertension, a different model of life-long renin overexpression produces HTN regardless of NOX1 or NOX2, possibly because chronically elevated Ang II causes developmental changes." (PMID 39765782, 2024). "While our study showed that potential adverse effects of Nox4/Nox1 pharmacological inhibition are pronounced in the vasculature in hypertension, the current study did not establish a clear answer to the problem of the relationship between perivascular inflammation and BP elevation in SHR." (PMID 33131726, 2020).
Hypertension (continued). "However, the role of Nox1 and Nox4 in the context of ageing, development of spontaneous hypertension and in modulation of the perivascular inflammation has not been investigated to date." (PMID 33131726, 2020). "Thus, the data regarding the role of NOX1 and NOX2 regarding preclinical hypertension are controversial and suggest that these isoforms may contribute to basal blood pressure regulation but not hypertension." (PMID 33170835, 2020). "In addition to the effects of GPER agonism via G-1, G36 prevented AngII-induced hypertension in mice through a unique mechanism resulting from the downregulation of Nox1 with the subsequent lack of reactive oxygen species production involved in AngII-induced vasoconstriction and thus hypertension." (PMID 36662583, 2023). "However, treatment of pre-hypertensive rats with the selective Nox1 inhibitor ML171 did not affect the development of spontaneous hypertension and had only a minor effect against perivascular leukocytes accumulation and chemokines level changes or adventitial fibrosis." (PMID 33131726, 2020). "Expression of VSMC NOX4, but not NOX1 or NOX2, was also increased in hypertension." (PMID 34320175, 2022). "Furthermore, we observed that the increase in PDI is accompanied by an increase in Nox1, but not Nox4, expression and that PDI plays a role in Ang II-induced redox signaling in hypertension." (PMID 25870854, 2015).
atherosclerosis (52 papers, 2013 to 2025). A disease characterized by the build-up of fatty material and calcium deposition in the arterial wall resulting in partial or complete occlusion of the arterial lumen. "In line, NOX1/NOX4 pharmacological inhibition and Nox1 deficiency significantly attenuate vascular ROS levels and atherosclerosis burden in ApoE−/− mice." (PMID 38952543, 2024). "For instance, global Nox1 deletion in mice was demonstrated to attenuate diabetes associated atherosclerosis." (PMID 33396868, 2020). "In ApoE−/− and NOX1−/− animals, a reduction in the atherosclerotic area and the macrophages within the plaque were observed, suggesting a crucial for NOX1-induced ROS formation in the pathogenic process of ApoE-mediated atherosclerosis." (PMID 30140678, 2018). "The protective effect of Nox1 deficiency was also observed in a mouse model of accelerated atherosclerosis induced by partial carotid ligation in C57Bl/6 mice fed high fat diet." (PMID 29710840, 2018). "Hyperglycemia, for example, can increase the expression of NOX1 in human aortic ECs, while inhibition of NOX1 in diabetic apolipoprotein-E (ApoE) deficient mice reduces atherosclerosis development." (PMID 28612009, 2017). "In Nox1-/y mice, a predominant role for Nox1-derived ROS was demonstrated in relation to diabetes-associated atherosclerosis." (PMID 29682485, 2017). "Inhibition of NOX1, implicated in the pathogenesis of restenosis and atherosclerosis, has been shown to significantly inhibit neointimal formation, and unlike NOX2 and NOX4, has been shown to be upregulated by bFGF in rat and mouse aortic SMCs." (PMID 25144362, 2014). "Global genetic deletion of Nox1 in ApoE KO deficient diabetic mice showed decreased macrophage infiltration and reduced plaque lesion size at the aortic valve through reduction in ROS formation, suggesting the pathological relevance of Nox1 in atherosclerosis." (PMID 34829831, 2021). "Furthermore, when fed an atherogenic diet for 18 weeks, Nox1 deficient mice, displayed decreased atherosclerosis, macrophage infiltration and reduced lesion size at the aortic valve compared those where Nox1 was intact." (PMID 33396868, 2020). "Preclinical studies demonstrated its dual renoprotective and atheroprotective effects in Apoe+ mice with STZ-induced diabetes, with NOX1 inhibition reducing atherosclerosis and NOX4 deletion unexpectedly increasing plaque area." (PMID 40076813, 2025). "NADPH oxidase organizer 1 (NoxO1) is a scaffold cytoplasmic subunit of the reactive oxygen species (ROS) forming Nox1 complex and involved in angiogenesis, differentiation, and atherosclerosis." (PMID 39426288, 2024). "In the HT group, excessive ROS production by Ang II-stimulated NOX1 activation can lead to abnormal angiogenesis, atherosclerosis, cellular senescence of VSMC, and endothelial dysfunction." (PMID 39459569, 2024). "NOX1 is also involved with the thickening of blood vessel walls, abnormal angiogenesis, atherosclerosis, and cellular senescence of VSMCs." (PMID 39459569, 2024). "Upregulated NOX1 in atherosclerosis has been demonstrated to promote vascular smooth muscle cell (VSMC) proliferation and extracellular matrix (ECM) production, inducing the formation of vascular neointima." (PMID 39867658, 2024). "In atherosclerosis, NOX1 is elevated early but declines later, while NOX4 increases in advanced stages." (PMID 39867658, 2024). "NOX1 ROS production is connected to multiple substances expressed via atherosclerosis, vasoactive agonists, pro-inflammatory cytokines, and atherogenic particles that cause continued NOX1-derived ROS production." (PMID 39858401, 2024). "Knockout NOX1 has been shown to delay the progression of atherosclerosis by reducing ROS production, suppressing inflammation, improving mitochondrial apoptosis, and alleviating endothelial cell dysfunction." (PMID 39867658, 2024).
atherosclerosis (continued). "Despite lacking of such clinical evidence in patients, selective downregulation of NOX1 also have a role in treatment of reperfusion injury in patients with atherosclerosis." (PMID 37134122, 2023). "Similar results were presented by Gray who demonstrated, in another inflammatory scenario, in the case of atherosclerosis, an increase in the expression of Nox-1 described in patient plates that had cardiovascular events or diabetes mellitus." (PMID 35928208, 2022). "High NOX1 expression activates macrophage infiltration and promotes systemic inflammatory responses, thereby accelerating atherosclerosis development in female mice." (PMID 36407440, 2022). "For instance, NOX1 is a major source of vascular ROS and accelerates atherosclerosis in diabetes by inducing vascular dysfunction and inflammation." (PMID 36009258, 2022). "Studies have also reported that diabetic APOE–/– mice can increase the NOX1 level by mediating the overexpression of ET-1, increasing the production of ROS in peri-aortic adipose tissue, and promoting atherosclerosis progression." (PMID 36407440, 2022). "Similar to NOX-1, the deficiency of NOX-2 has also been confirmed to reduce the occurrence of atherosclerosis." (PMID 35047104, 2022). "Another study using GKT137831, a dual inhibitor of NOX1/4 in streptozotocin induced diabetic ApoEKO mouse model showed protection against atherosclerosis by reducing aortic plaque formation and inflammation via reduction in ROS formation." (PMID 34829831, 2021). "In summary, the general trend for the attenuation of atherosclerosis by berries is due to reduced oxidative stress (improved antioxidant capacity and reduced Nox1)." (PMID 32664664, 2020). "Whereas two studies suggest that ApoE/Nox1 double knockout mice developed less atherosclerosis one study observed the opposite." (PMID 32949971, 2020). "Previous studies have shown that NOX1 and NOX4, with proinflammatory actions, are implicated in the pathogenesis of cardiovascular disease and are highly associated with atherosclerosis." (PMID 32218307, 2020). "Gray and colleagues previously suggested that genetic deletion of Nox2 was potentially lethal and that the Nox1 isoform of NADPH oxidase was a more appropriate target to slow the development of atherosclerosis in diabetic mice." (PMID 32401607, 2020). "Although Nox1 with its cytosolic co-factors are largely expressed in epithelial cells, a role for Nox1 for atherosclerosis development was suggested." (PMID 32949971, 2020). "It has been shown that combined Nox1/4 inhibition with GKT137831 reduces vascular leukocytes infiltration in atherosclerosis, or suppresses proinflammatory and profibrotic processes in a model of diabetic nephropathy, both results are contrary to our study." (PMID 33131726, 2020). "Vascular Nox1/2-derived ROS has also been suggested in atherosclerosis, diabetic vasculopathy, vascular remodeling, and aortic aneurysm." (PMID 30334629, 2019). "Reports in the literature support the idea that Nox4 is protective, while Nox1 is deleterious for atherosclerosis development." (PMID 29710840, 2018). "Genetic deletion of Nox4 in ApoE−/− mice increased atherosclerosis after 20 weeks of diabetes mellitus induction, while deletion of Nox1 in the same conditions reduced atherosclerosis." (PMID 29710840, 2018). "Nox1 affects atherosclerosis formation, as Nox1 genetic deletion in ApoE−/− mice reduces atherosclerosis." (PMID 28971272, 2018). "This review focuses on the role of the mitochondria and the nicotinamide adenine dinucleotide phosphate (NADPH) oxidases Nox1 and Nox4 in vascular senescence, and their contribution to the development of atherosclerosis." (PMID 29710840, 2018). "Research has demonstrated that NADPH oxidase 1 (NOX1) acts as a pro-atherogenic and pro-oxidant factor, while NOX4 exhibits atheroprotective properties in STZ-induced diabetic Apoe+ mice, a widely used model for studying diabetes-associated atherosclerosis." (PMID 40076813, 2025).